PDHX (pyruvate dehydrogenase complex component X)
Description:
Required for anchoring dihydrolipoamide dehydrogenase (E3) to the dihydrolipoamide transacetylase (E2) core of the pyruvate dehydrogenase complexes of eukaryotes. This specific binding is essential for a functional PDH complex.
Synonyms: E3BP; PDX1; proX; OPDX; DLDBP; PDHXD
Tractability: Small molecule: a structure with a bound ligand is known. Antibody: its Gene Ontology location is reachable by antibodies, with high confidence. PROTAC: ubiquitination databases record sites on it; its protein half-life has been measured.
Gene: Protein-coding gene on chromosome 11 (34,915,829 to 35,020,591, forward strand). Ensembl gene ENSG00000110435.
Subcellular location: Mitochondrion matrix
Subcellular location (Human Protein Atlas): Mitochondria; Nucleoplasm; Plasma membrane
Pathways (Reactome):
Metabolism: PDH complex synthesizes acetyl-CoA from PYR; Regulation of pyruvate dehydrogenase (PDH) complex
Signal Transduction: Signaling by Retinoic Acid
Gene Ontology:
Molecular function: dihydrolipoyllysine-residue acetyltransferase activity; protein binding; acyltransferase activity
Biological process: pyruvate decarboxylation to acetyl-CoA
Cellular component: mitochondrion; pyruvate dehydrogenase complex; mitochondrial matrix
Genetic constraint (gnomAD): Loss-of-function variants: 19 observed, 34.98 expected, observed/expected ratio (o/e) 0.54, 90% interval 0.38 to 0.8. The upper end of that interval is the gene's LOEUF score, 0.8, which puts it in group 3 of 6, group 1 being the genes least tolerant of losing a copy. Missense variants: 445 observed, 462.94 expected, observed/expected ratio (o/e) 0.96, 90% interval 0.89 to 1.04. Synonymous variants: 178 observed, 167.04 expected, observed/expected ratio (o/e) 1.07, 90% interval 0.94 to 1.21.
Gene-disease validity (ClinGen):
ClinGen rates the evidence that PDHX causes each of these diseases.
Leigh syndrome (autosomal recessive): Definitive. A progressive neurological disease defined by specific neuropathological features associating brainstem and basal ganglia lesions.
mitochondrial disease (autosomal recessive): Definitive.
Homologues: Orthologues: chimpanzee PDHX (99% identical), macaque PDHX (99% identical), dog PDHX (90% identical), pig PDHX (88% identical), rabbit PDHX (87% identical), mouse Pdhx (85% identical), guinea pig PDHX (79% identical), rat Pdhx (59% identical), tropical clawed frog pdhx (58% identical), zebrafish pdhx (54% identical), Caenorhabditis elegans dlat-2 (26% identical). Paralogues in human: DLAT (40% identical), DLST (23% identical), DBT (22% identical).